ENSG00000251838
Gene: Small nucleolar RNA gene on chromosome 11 (37,702,125 to 37,702,220, reverse strand). Ensembl gene ENSG00000251838.
Homologues: Paralogues in human: SNORA31B (82% identical), SNORA31 (66% identical).